CD68 (CD68 molecule)
Diseases named in the same sentence as CD68 in open-access papers (continued):
Sharing a sentence is not in itself a finding about the gene and the disease.
diabetes (50 papers, 2011 to 2025). "Similarly, CD68+ pancreatic islet macrophages (PLMs) are increased in diabetic patients, and their accumulation is associated with the pathogenesis of type 2 diabetes mellitus (T2DM) in humans, such as amyloid deposition." (PMID 36814909, 2023). "The results showed that the levels of CD68 was significantly enhanced in diabetes-induced atrophic muscle, and it was reduced after celecoxib treatment." (PMID 38313305, 2024). "Diabetes and irradiation significantly increased number of CD68 positive macrophages in submucosa and muscles." (PMID 38238729, 2024). "In comparison to the control group, the levels of F4/80, CD68, and CD68/(F4/80) mRNA were considerably elevated (p < 0.01) in the diabetes model group." (PMID 38560269, 2024). "The pan-marker CD68, proinflammatory marker iNOS, and novel markers TREM2 and CD9 are widely used markers in macrophages that are strongly associated with obesity and diabetes." (PMID 36814909, 2023). "Eight weeks after diabetes induction, the number of cells positive for the panmacrophage marker CD68 was increased in the SN of diabetic mice compared with that of their nondiabetic counterparts, despite the difference in genotypes." (PMID 36477360, 2022). "This study also demonstrated an increased expression of the inflammatory marker CD68 in the rat livers along with the increase of diabetes duration, suggesting involvement of macrophage cell lineage recruitment in the diabetic livers." (PMID 36818894, 2022). "Macrophage infiltration in diabetic kidneys, as detected by CD68 staining, was suppressed in response to drug treatment." (PMID 35918533, 2022). "We conclude that mAb 17D5 delayed diabetes in DRLyp/Lyp rats and markedly reduced expression of HA and concomitant infiltration of CD68+, CD3+, and CD8+ cells." (PMID 33815287, 2021). "This is accompanied by increases in LV gene expression of Tnfα, concomitantly with the macrophage marker Cd68 and increased macrophage content in the diabetic heart from 8 to 12 weeks of diabetes." (PMID 32153425, 2020). "Post-mortem studies of atherosclerotic lesions from both subjects with T1DM and T2DM suggest that diabetes increases the abundance of CD68-positive lesion cells likely to be macrophages." (PMID 32118048, 2020). "LV gene expression of CD68 was increased overall by diabetes (P = 0.003) and was increased by 16 weeks of diabetes (P < 0.05)." (PMID 32153425, 2020). "Compared with the diabetes group, immunohistochemistry staining showed there was a remarkable decreasing of CD68 positive cells and TUNEL positive cells in the atherosclerotic plaques in the liraglutide group." (PMID 29213335, 2017). "The previous study demonstrated that CD68-positive monocytes displayed increased attachment to endothelium in diabetes, which damaged the endothelial glycocalyx." (PMID 29207649, 2017). "We further observed that maternal obesity together with diabetes exaggerated inflammatory cell accumulation in the kidney, as seen by increases in both CD68 and F4/80." (PMID 27277011, 2016). "Using the Reversa mouse model, we have previously reported that diabetes hindered plaque regression in atherosclerotic mice (based on CD68+ plaque content) and impaired favorable changes in plaque macrophage characteristics." (PMID 26046657, 2015). "The majority of the splenic cytokines in response to the elevated glucose in early and late diabetes are macrophage-derived where the expanded CD68+F4/80− subpopulation is the predominant producer." (PMID 24594974, 2014). "In early stages of diabetes the frequency and hence number of TNFα producing CD68+F4/80− macrophages are higher compared to healthy control mice." (PMID 24594974, 2014).
diabetes (continued). "Notably, however, we do find elevated inflammatory pathways in SQ adipose of those with diagnosed diabetes and more CD68+ macrophages, which suggests that there are differences in inflammation in other adipose depots between these groups." (PMID 41245395, 2025). "Further examination uncovered enhanced infiltration of CD68-positive macrophages in the renal tissues of diabetic Trex1−/− rats, supporting the conclusion that Trex1−/− rats develop diabetic nephropathy after onset of diabetes." (PMID 38166933, 2024). "Diabetes induced an increase of CD68-positive cells in the livers of the DM groups." (PMID 36818894, 2022). "Also, islet-associated CD68+ and CD3+ cells occurred less frequently (on average in 60 and 3% of the islets, respectively) than in the diabetes rats (present in >95% of the islets)." (PMID 33815287, 2021). "Systemic and local inflammation (TNFα, IL-1β, CD68) were increased with diabetes." (PMID 32153425, 2020). "This was accompanied by an overall increase in LV CD68+ stained macrophages with diabetes (P = 0.012), an increase at 12 weeks, and a tendency to be increased at both 8 and 16 weeks of diabetes on post hoc analysis (P = 0.07 and P = 0.06, respectively), as measured by immunohistochemistry." (PMID 32153425, 2020). "Furthermore, levels of the macrophage marker CD68 were significantly increased by diabetes (P < 0.01, HC-ctrl vs. HC- T1D) and maternal obesity (P < 0.05, CC-ctrl vs. CC-T1D)." (PMID 27277011, 2016). "Taken together, these data indicate that diabetes affects the uninjured sensory neurons, and Schwann cells and has a negative effect on axonal outgrowth and on the numbers of activated Schwann cells and CD68 pan-macrophages after nerve injury and nerve reconstruction with autografts." (PMID 40260416, 2025). "Islet-associated CD68+ cells were observed in the pancreata of the three 17D5 no-diabetes rats." (PMID 33815287, 2021). "Eight studies investigated monocytes/macrophages in the liver under diabetes, using nine markers to identify monocytes/macrophages in mice (CD11b, Ly6C, F4/80, CD11c, CD206, and CD86) and humans (CD14, CD16, and CD68) at protein or RNA levels." (PMID 40362271, 2025). "However, increased staining for CD68 was statistically significant within the DRG of those with DPN, demonstrating that the upregulated inflammatory markers captured in the transcriptomics are likely linked to innate immune responses, potentially stemming from diabetes related neuronal pathology." (PMID 35304484, 2022). "Diabetes + STD rats showed that the mRNA expression of type 3 collagen (Col3), Kim-1, Cd68 and tumor necrosis factor-α (Tnf-α) in the renal cortex was significantly increased compared to that in the control." (PMID 32145700, 2020). "The expressions of CD68, caspase-3, CHOP and GRP78 in aorta tissue samples were significantly downregulated in the liraglutide group than that in the diabetes group." (PMID 29213335, 2017). "However, in the presence of EC-NOX5 expression, there was an increased number of glomerular CD68-positive cells and increased renal MCP-1 levels in cases of diabetes." (PMID 38671844, 2024). "Differentially regulated genes not overlapping with ERCB data also reflected diabetes-associated changes, such as extracellular matrix (ANGPTL4, TNN, DPT, COL9A2) or gestational diabetes (LAT2, HP, CXCL10, CD86, CD68, REN, SLC2A3, VCAM1)." (PMID 33923831, 2021). "When dividing the group into plaques from patients with or without T2D, CD68 only correlated to oxLDL levels (r = 0.2, p = 0.03) in plaques from patients without diabetes." (PMID 33317535, 2020). "Although oxLDL only correlated to CD68 in plaques from patients without diabetes, it did correlate to pro-inflammatory cytokine levels in both groups." (PMID 33317535, 2020).
diabetes (continued). "After diabetes manifestation, the islet infiltrate was composed of a high number of both immune cell types, CD8+ T cells and CD68 macrophages, and to a lesser extent of around 10 % CD4+ T cells as well as 10 % of NK-cells and B cells in the acutely diabetic rats." (PMID 32607871, 2020). "Shown in Figure B in S1 File at day 6 the percentage of macrophages (CD68 positive) was not altered by diabetes." (PMID 28182694, 2017). "A previous study found that CD68, a macrophage marker, was higher in the DRGs of patients with DPN, demonstrating that the upregulated inflammatory markers may contribute to the inflammatory response, potentially stemming from diabetes related neuronal pathology." (PMID 36671424, 2022). "Similarly, renal gene expression of Il1β, Il18 and Ccl2 as well as glomerular accumulation of CD68-positive cells, which is a macrophage marker, were increased in the MCC950-treated diabetic animals, consistent with MCC950 promoting renal inflammation in diabetes." (PMID 35048962, 2022). "Among rats without diabetes at 100 days of age there was a reduction in CD3+ and CD8+ T cells, reduction in CD68+ cells, and reduced HA deposition." (PMID 33815287, 2021). "We analyzed the mRNA expression of SRs (LOX-1, MSR1, CXCL16, CD36 and CL-P1) and macrophage markers (CD68, CD11c and CD206) in EAT from 45 patients with IHD (23 with type 2 diabetes mellitus (T2DM) and 22 without T2DM) and 23 controls without IHD or T2DM." (PMID 30894181, 2019). "Numbers of CADM1+CD68+ peri-islet myeloid cells adjacent to CD8+ T cells were also increased in pancreatic sections from both T1D and aAb+ donors compared with individuals without diabetes." (PMID 35133983, 2022). "To investigate if increased glucose flux into myeloid cells per se could mimic the effects of diabetes in non-diabetic mice, we overexpressed GLUT1 under control of the CD68 promoter in hematopoietic cells, which results in expression primarily in myeloid cells." (PMID 32118048, 2020).
colon carcinoma (43 papers, 2013 to 2025). "A disease association of BMMF with colon cancer was tested by coimmunofluorescence quantification of Rep and CD68+ cells in peritumor colon tissue (n = 7) and control tissues of younger asymptomatic donors (n = 8, 18 to 24 y, median age 21.1 y)." (PMID 33723077, 2021). "In 521 patients with stage II colon cancer after radical resection, low CD68+ TAM density was significantly associated with perineural invasion." (PMID 33194645, 2020). "The recovery of a BMMF1 isolate H1MSB1 from the peritumoral lamina propria cells of colon cancer patients with CD68 macrophage invasion also demonstrates the association of these agents to infections of the colon." (PMID 31409221, 2019). "The AOM/DSS group showed weight loss, diarrhea, intestinal shortening, increased number of colon tumors, proliferating tumorigenesis, increased inflammation score, fibrosis, increased CD68+, or CD163+ macrophage cells in the subserosal layer of non-tumor areas." (PMID 33808480, 2021). "Samples and corresponding clinical information of 32 colon cancer patients with lung metastasis were collected, and the CD68, CD163, and SOCS3 status were conducted using immunohistochemistry (IHC)." (PMID 37025997, 2023). "DKC1 expression was positively correlated with the macrophages marker, CD68, at the invasive front of colon cancer tumors." (PMID 36428700, 2022). "In our study, we cocultured CD68+CD163+ TAMs with colon cancer cells with different RBP‐Jκ expression." (PMID 34655278, 2021). "The CD68 antigen was similarly significantly higher in colon cancer patients compared to younger cancer-free controls." (PMID 33723077, 2021). "Macrophage recruitment to neoplastic mucosa was determined with the evaluation of CD68 antigen expression in the colon tumours." (PMID 34679712, 2021). "Quantification of Rep+ and CD68+ interstitial cells was performed, demonstrating a significant increase in Rep+ cells in colon cancer patients compared to younger cancer-free donors." (PMID 33723077, 2021). "This suggests that the CD206/CD68 ratio is probably a better biomarker for prognosis and prediction of stage II colon cancer after adjuvant chemotherapy." (PMID 34445193, 2021). "As high CD163 expression was associated with cancer metastasis, we assessed the effects of CD68+CD163+TAMs on colon cancer cells." (PMID 34655278, 2021). "In stage II colon cancer with high CD206/CD68 ratio, adjuvant chemotherapy significantly improved the DFS rate from 38.9 to 68.0% at 3 years and from 33.1 to 66.0% at 5 years." (PMID 33194645, 2020). "Tissue microarray of 100 patients with colon cancer (Germany) demonstrated that amounts of CD68+ macrophages were decreased at higher stage tumors." (PMID 33194645, 2020). "Significantly higher numbers of CD68+ cells were observed in colon cancer tissue compared with normal colon mucosa." (PMID 31601783, 2019). "The numbers of CD68+ cells were similar in colon cancer tissues of different AJCC stages but the numbers of CD206+ / CD163+ cells were higher in late stage tumors and the number of iNOS+/CD86+ cells was higher in early stage tumors." (PMID 29368606, 2018). "We used immunohistochemistry to detect the protein expression of MUC2, IL-6, and CD68 in serial sections of colon cancer tissues." (PMID 28725043, 2017). "CD68-positive macrophages were located in the stroma of adenomatous polyps, while in colon carcinoma, they were in the stroma and in particular along the tumor front." (PMID 27275223, 2015). "Cat S-positive cells within the area colocalized with CD68-positive macrophages, indicating a high concordance of CD68 and Cat S expression in human primary colon carcinoma during malignant progression." (PMID 24580730, 2014). "PFKFB3+CD68+ correlated with unfavorable prognosis specifically in colon cancer." (PMID 41516095, 2025).
colon carcinoma (continued). "CD68 staining indicates the presence of macrophages and histiocytes, meaning reactive processes within the celiac ganglion, likely related to inflammation in the case of dysautonomia and colon cancer." (PMID 40134445, 2025). "Moreover, immunofluorescence staining of human colon cancer samples validated the presence of CD68+ macrophages that coexpressed TGF-βRI and PD-1." (PMID 38441961, 2024). "Above results, it is not difficult to find that SPOCK1 and POSTN related to CAF are co-expressed with CD68 and CD206 in colon cancer, which indicates that the CAF-associated POCK1 and POSTN expressions have an important influence on macrophages, especially M2 macrophages." (PMID 36611136, 2023). "Furthermore, advanced colon carcinoma tissues were markedly and extensively infiltrated by CD68-positive macrophages, particularly along the tumor cell-invasive front, while few macrophages were observed in normal colon tissues." (PMID 24580730, 2014). "In addition, the advanced colon carcinoma tissues were markedly and extensively infiltrated by CD68-positive macrophages, particularly along the tumor cell-invasive front; however, the number of macrophages in normal colon tissues was low." (PMID 24245985, 2013). "We followed the fate of PFKFB3+ monocytes in colon cancer, and using spatial transcriptomics demonstrated their massive infiltration and differentiation into PFKFB3+CD68+." (PMID 41516095, 2025). "For example, CD68+ and CD163+ macrophages have been demonstrated to exert different effects on the prognosis of stages I-III colon cancer patients, highlighting the importance of characterizing macrophage subtypes in CRC." (PMID 40740776, 2025). "The human colon cancer tissues data downloaded from TIMER also showed that SPOCK1 and POSTN were positively correlated with CD68 and CD206 in colon cancer tissues." (PMID 36611136, 2023). "The infiltration of CD8+ T cells was more but the proportions of CD68+ cells (macrophages), α-SMA+ cells (CAFs) and CD31+ cells (endothelial cells) were fewer in human colon cancer tissues with low CYP19A1 expression as compared with high CYP19A1 expression." (PMID 37055842, 2023). "In the colon cancer tissue itself, 65% of dendritic cells, 30% of CD45 positive cells, 5% of CD11b positive cells, and 20% of CD68 positive cells were found (for a summary of the results)." (PMID 33921688, 2021). "The positive correlation between CD68 and HIF1A, and the increased CA9 and LOX expression in CD68HighHIF1AHigh patients were validated on the Oncomine database (colon cancer Bittner cohort, with the highest number of patients)." (PMID 32231135, 2020). "As previously demonstrated in a studyof colon cancers, hGBP -1 can also be expressed within endothelial cells (CD31) and monocytes (CD68) within the tumors." (PMID 28090373, 2016). "Immunostaining for CD68 and Factor VIII was evaluated in 15 benign adenomatous polyps and 44 cases of colon carcinoma." (PMID 27275223, 2015). "CX3CR1-positive cells within the area colocalized with CD68-positive macrophages, indicating a high concordance of CD68 and CX3CR1 expression in human primary colon carcinoma during malignant progression." (PMID 24245985, 2013). "However, TAM infiltration alone was not highly significant in prognostic analysis, while the presence of both CD68- and VEGF-expressing TAMs was predictive of better survival rates in stage II and stage III colon cancer patients." (PMID 34445193, 2021). "Furthermore, the expression level of CD68 was significantly increased in the cancer tissues with high expression of SERPINE2, suggesting that the high expression of SERPINE2 in colon cancer may promote macrophage infiltration." (PMID 40463876, 2025). "To assess how the mouse model for metastatic colon cancer described in this report reflects these site-specific differences in the tumor microenvironment, we performed immunohistochemistry analysis to detect blood vessels (CD31), macrophages (CD68), and vitronectin." (PMID 38473429, 2024).
colon carcinoma (continued). "In non-neoplastic colonic mucosae as well as colon cancer stroma, TAIs positive for SIRPA, CD68, or CD163 were variably observed." (PMID 33799989, 2021). "In the colon cancer tissue itself, 5% of dendritic cells, 20% of CD45 positive cells, 30% of CD11b positive cells, and no CD68 positive cells were found." (PMID 33921688, 2021). "In the colon cancer tissue itself, 50% of dendritic cells, no CD45 positive cells, 10% of CD11b positive cells, and no CD68 positive cells were found." (PMID 33921688, 2021). "In the colon cancer tissue itself, 10% of dendritic cells, no CD45 positive cells, 5% of CD11b positive cells, and no CD68 positive cells were found." (PMID 33921688, 2021).